RNU6-353P (RNA, U6 small nuclear 353, pseudogene)
Gene: Small nuclear RNA gene on chromosome 15 (43,702,363 to 43,702,470, forward strand). Ensembl gene ENSG00000201136.
Homologues: Orthologues: macaque U6 (91% identical), dog U6 (82% identical), pig U6 (77% identical), pig U6 (76% identical). Paralogues in human: RNU6-554P (88% identical), RNU6-116P (86% identical), RNU6-1060P (85% identical), RNU6-33P (85% identical), RNU6-47P (85% identical), RNU6-1 (84% identical), RNU6-15P (84% identical), RNU6-2 (84% identical), RNU6-3P (84% identical), RNU6-4P (84% identical), RNU6-5P (84% identical), RNU6-6P (84% identical), and 1285 more.